MYC (MYC proto-oncogene, bHLH transcription factor)
Diseases named in the same sentence as MYC in open-access papers (continued):
Sharing a sentence is not in itself a finding about the gene and the disease.
tumor (continued). "For example, in Case #39, the clonal prevalence of the subclone labelled G, containing mutations in FGFR1, KMT2D, MYC driver genes, was ~0.27 in the pre-treatment tumour biopsy, decreased to ~0.22 in post cycle 1 treatment tumour biopsy but increased to ~0.34 in the lymph node biopsy." (PMID 37758711, 2023). "As the direct targeting of MYC is proven to be challenging due to its relatively high toxicity, understanding its underlying regulatory mechanisms is essential for the development of tumor-selective targeted therapies." (PMID 37443779, 2023). "Additionally, to understand the role of MYC overexpression in OS regulating Csf1r expression in tumor-associated macrophages, we analyzed their expression at transcription and protein levels." (PMID 37279073, 2023). "The association of high MYC expression and increased progression-free survival suggests that these tumor-suppressive functions of CCAT1 and CCAT2 are mediated through their target MYC, a notion that is backed up by further in vitro analyses presented in this study." (PMID 37347737, 2023). "Additionally, ITGA5 levels appeared to be higher in Group 3 MB, a MYC-driven subtype associated with the increased frequency of tumor recurrence and leptomeningeal dissemination, when compared to other subtypes." (PMID 37430373, 2023). "Therefore, it is a crucial oncogene element involved in tumor progression and c-MYC deregulation caused by mutations in APC in CRC." (PMID 36843070, 2023). "In summary, since splicing factor‐mutated and MYC‐driven tumours are more sensitive to splicing modulation, CDK11 inhibition could represent a novel synthetically lethal interaction for such splicing‐dependent cancers." (PMID 36855776, 2023). "Specifically, dysregulations of MYC proteins are associated with 70% of human cancers, and a wealth of evidence suggests that aberrantly expressed MYC proteins are closely related with both tumor initiation and maintenance." (PMID 37554307, 2023). "Indeed, MYC was linked to the activation of an embryonic stem cell-like program in differentiated adult epithelial cells and thus, implicated in tumor initiation and the self-renewal capability of cancer stem cells." (PMID 37400551, 2023). "In addition, the GSVA results in our study showed that pathways enriched in subsets 0 and 3 included Hedgehog signaling, notch signaling, angiogenesis, and MYC pathways, which are associated with tumor proliferation and progression." (PMID 37221625, 2023). "However, increased gene dose of the KRAS oncogene as well as the amplification or activation of MYC have been linked to tumor progression and metastasis." (PMID 37659057, 2023). "Additionally, MYC influences the recruitment of myeloid-derived suppressor cells (MDSCs) and tumor-associated macrophages (TAMs)." (PMID 37755397, 2023). "When the authors reduced serum and tumor tissue lysine levels in healthy or tumor-bearing NOD.SCID γc-deficient mice with a lysine-restricted diet, MYC inhibition by the small molecule MYCi975 in combination with this diet improved their survival and diminished tumor cell counts." (PMID 37813874, 2023). "Additionally, the transcription factor c-MYC, commonly used in pluripotency induction, is inherently tumorigenic and closely linked to tumor formation and invasion." (PMID 36979334, 2023). "Dysregulation of MYC expression is most associated with aggressive tumor growth and malignancy." (PMID 37404312, 2023). "To see whether a drop in ʟ-arginine concentration associated with tumor progression leads to impaired T-cell proliferation, we have adoptively transferred OT-I cells into control and Vκ*MYC-bearing mice and challenged mice with OVA." (PMID 36385153, 2022).
tumor (continued). "In addition, Wnt pathway can regulate decomposition of glutamine and synthesis of nucleotide in tumor tissues by targeting MYC to participate in NM, causing NMD." (PMID 35903696, 2022). "Therefore, the tumour-promoting effect conferred by the triple mutation T81P/S101P/L123S on the HBx protein is dependent on the expression of MYC." (PMID 36102940, 2022). "Taking into account the possibility of carcinogenic events associated with frequent genetic modifications in signalling pathways, we determined the amount, mechanism and co-occurrence of mutations in the c-MYC pathway across various tumour types and subtypes, as depicted in the heatmap." (PMID 35801728, 2022). "Among them, compound CGP.082996 was found to be associated with the MYC locus, suggesting that it is a potent antiproliferative agent against retinoblastoma- (Rb-) positive tumor cells by exclusively arresting cells at G1 and reducing phospho-Ser 780/Ser 795 on the Rb protein." (PMID 35028006, 2022). "Though PD-L1 was present on tumor-associated immune cells in the MYC-driven TNBC model, the poor tumor response to anti-PD-L1 led us to postulate that other factors might explain the observed immune evasion." (PMID 35760778, 2022). "Suppression of MYC may cause tumor cells to lose their neoplastic properties, because of diverting cellular resources toward stress response pathways, permitting cells to recognize DNA damage, leading to enforces their regression and differentiation." (PMID 35705657, 2022). "Recently, three additional signatures associated with MYC and tumor microenvironment were reported." (PMID 35267654, 2022). "Thus, the authors suggested that DNMT1 was implicated in the maintenance of the tumor phenotype in MYC-induced T-cell lymphomas and in the de novo methylation during tumorigenesis." (PMID 35326620, 2022). "However, the association of MYC activation and an immunosuppressive environment as seen in low lymph node yield tumours has previously been described in other solid organ malignancies." (PMID 35043009, 2022). "Notably, Hira depletion in Fh1-deficient cells controls the activation of an MYC- and E2F-dependent transcriptional and metabolic program, which is known to play different oncogenic roles during tumor initiation and progression." (PMID 36269833, 2022). "In addition, we found MYC CN gains to be significantly associated with increased relative frequency of duplication per tumour (adjusted p-value = 0.03), with four of the hyper-duplicated tumours presenting with MYC CN gains." (PMID 36045381, 2022). "Given our data suggesting that MYC inhibition would be effective independently of the mutational profile of the tumor, using this approach could overcome this heterogeneity barrier." (PMID 36860495, 2022). "Hence, the HBx protein harbouring triple mutation T81P/S101P/L123S can elevate the level of MYC via the transcription and post-translation processes compared with wild-type HBx, indicating an underlying tumour-promoting effect of HBx-T81P/S101P/L123S." (PMID 36102940, 2022). "Yet, administration of the same dose of GSK126 caused MYC depletion and tumor growth inhibition in NCI-H82 xenografts, indicating that GSK126 at these doses may disrupt EZH2-MYC interaction and induce MYC degradation in vivo." (PMID 35013218, 2022). "Subsequent evidence showed that it could result in tumor progression and poor prognosis via activating cell cycle, DNA repair, MYC, and KRAS-associated signaling pathways as well as rendering immune dysregulation." (PMID 36522647, 2022).
tumor (continued). "We hypothesize that poor efficacy of anti-PD-L1 therapy in TNBC is linked to MYC-driven tumor cell immune evasion." (PMID 35760778, 2022). "The MYC gene family is highly involved in tumors in which they are often dysregulated and mutated (manly by translocations or gene amplification), resulting in overexpression and association with tumor aggressiveness and poor prognosis." (PMID 35890348, 2022). "Between the two tumor cohorts, we observed significant overlap between the respective gene-level associations (p < 5E−8, one-sided Fisher’s exact test), involving 12 genes, all of which were enriched for mutation events in tumors with high MYC signature." (PMID 35562349, 2022). "Additionally, MYC is one of the most commonly activated oncogenes in human and canine tumours being associated with tumourigenesis and sustained tumour growth." (PMID 36054794, 2022). "As for PVT1, the corresponding lncRNA of MYC, although it was confirmed to be associated with a variety of malignancies and promote tumor cell proliferation, migration, tumor growth and metastasis, and adipogenic potential, the lipid metabolism of PVT1 regulating is still unclear." (PMID 35501901, 2022). "In addition, high expression of NFS1, transcriptionally regulated by MYC, was found in tumor tissues and was associated with poor survival and hyposensitivity to chemotherapy in patients with CRC." (PMID 35221331, 2022). "The inactivation of MYC triggers tumor regression through the loss of hallmark features of cancer." (PMID 36389789, 2022). "To investigate the molecular framework underlying a potential PGC transformation into MYC tumor cells, we compared single cell transcriptomes of the latter with PGCs from various developmental stages between E6.75 and E16.5 (in total 15,106 single cells), and performed DE analysis." (PMID 35318328, 2022). "Another example of how MYC tempers inherent RS is reported in breast cancer stem cells (CSCs), where the collision between transcription and replication machineries is frequent and the major cause of RS in tumor spheroids." (PMID 34201047, 2021). "Moreover, some in vitro studies demonstrated that MYC is a key element in tumor progression and treatment resistance of BRAF-mutated CRC." (PMID 34943546, 2021). "Similarly, c-MYC is a key player in alternative macrophage activation in the tumor microenvironment, and contributes to tumor-promoting functions of tumor-associated macrophages." (PMID 34921160, 2021). "In addition, key molecular features of a tumor type, such as MYC amplification in Gr.3-MB or H3.3G34 mutations in HGG, were significantly associated with high numbers of CD8+ T cells and B cells, and CD8+ T cells, respectively." (PMID 34830753, 2021). "Other signatures were also identified in this analysis that implicates previously unreported processes in Vκ*MYC disease biology including signatures related to knockdown of the tumour suppressor TCF21, KRAS mutations, and constitutive activation of the RHOA oncogene." (PMID 34732728, 2021). "Depending on the activating/repressive function of individual transcription factors, IDR-mutated proteins can be both oncogenes (with MYOD1 mutations promoting the dimerization with MYC), or tumor suppressors (with ID3 mutations impairing its repressor activity)." (PMID 33806614, 2021). "Our studies establish MGA as a bona fide tumor suppressor in vivo and suggest a tumor suppressive mechanism in adenocarcinomas resulting from widespread transcriptional attenuation of MYC and E2F target genes mediated by MGA-MAX associated with a non-canonical Polycomb complex." (PMID 34236315, 2021).
tumor (continued). "TNBC tumors exhibit elevated MYC expression and altered expression of MYC regulatory genes, which are associated with tumor progression and poor prognosis; however, the underlying mechanisms by which MYC retains its high expression and mediates TNBC tumorigenesis require further exploration." (PMID 33541412, 2021). "Further molecular analysis revealed that MYEOV acts as a tumor promoter by associating with MYC to facilitate oncogenic miR-17/93-5p expression in PDAC progression and may provide a potential therapeutic strategy for PDAC patients." (PMID 34930894, 2021). "Stabilization of MYC by O-GlcNAcylation promotes cell growth under nutrient-rich conditions but causes activation-induced death in nutrient- and growth factor-poor conditions that can exist in a tumor microenvironment." (PMID 34868034, 2021). "c-MYC downregulation has been linked to increased anti-tumor immune response." (PMID 34947972, 2021). "Alternatively, the universality of chr5 loss reported in our study may be explained by the use of Vκ*MYC mice backcrossed onto C57BL/KaLwRij mice since tumours derived from this strain (5TMM) also demonstrate loss of chr535,54,55." (PMID 34732728, 2021). "In addition, tumor cell heterogeneity can contribute to the emergence of clones that have acquired additional mutations that allow MYC-independent growth." (PMID 33760847, 2021). "Notably, Wnt signaling causes tumor therapeutic resistance via the synergistic interaction between Wnt target gene c-MYC and HIF-1α which can subsequently attenuate the responsiveness of cancer cells to the drugs combating them." (PMID 34376211, 2021). "And NAA25 knockdown could increase apoptosis associated pathways, and reduce tumor associated pathways, like MYC, HIF1A, ERB2, MEK and TNF." (PMID 35096568, 2021). "Of these, 13 had either MYC-amplified/β-catenin-mutated tumours." (PMID 33020594, 2021). "Furthermore, the amplification of MYC genes is mutually exclusive, and the switch of gene expression among the members is associated with cell lineage shift, tumor progression, and treatment resistance." (PMID 33614505, 2020). "Moreover, the overexpression of c-MYC, a central oncogene driving many tumours and super-enhancer-associated transcription factor genes, including RUNX1 and MYB, depends on CDK12." (PMID 34316683, 2020). "Furthermore, we found that MYC inhibition can decrease Cd47 in tumor-associated macrophages in vitro." (PMID 32685002, 2020). "Mannose receptors are directly up-regulated by c-MYC in tumor-associated macrophages." (PMID 33081056, 2020). "The MYC oncogene, which is frequently deregulated among multiple human malignancies, encodes the oncogenic transcription factor c-Myc to drive tumorigenesis associated with cellular proliferation, DNA replication and transcription, protein synthesis and altered tumor cell metabolism." (PMID 33117704, 2020). "We hypothesized that higher scores of MYC targets v1 and MYC targets v2 would be associated with higher rates of cell proliferation, causing increased tumor aggressiveness and worse survival." (PMID 33143224, 2020). "Tumor associated macrophages are required for Twist1 to induce metastasis of MYC-HCC." (PMID 31933479, 2020). "In this cell line, the concordant anti-MYC action of ATRA and DAPT may be one of the major mechanisms underlying the anti-tumor action of the two compounds, as MYC is a well-known regulator of cancer cell stemness." (PMID 33081033, 2020).
tumor (continued). "One of the major consequences of MYC activation is the extensive reprogramming of the expression pattern of miRNAs in tumor cells, which is closely linked to the modulation of critical pathways associated with cancer etiology, including MYC-MAX-MXD1 and Ras-ERK pathways." (PMID 32150871, 2020). "In addition to its different effects on NK cells, MYC was found to impair innate immunity by its effects on tumor-associated macrophages (TAMs)." (PMID 33092116, 2020). "Research in subsequent decades implicated increased MYC in progression of most tumours." (PMID 32527935, 2020). "In addition to MYC, many tumor-associated genes such as RUNX1, FOSL2, BCL3 and ID2 are driven by SEs in diverse tumor types." (PMID 33628735, 2020). "Similarly, MGA normally subdues the activity of well-known oncogene MYC; its frequent deletion, truncation, or mutated binding properties across cancers further indicates its role as a tumor suppressor." (PMID 32711844, 2020). "Likewise, colon tumors, which express high MYC levels because of loss-of-function mutations in the APC tumor suppressor gene, depend on NUAK1 for tumor growth and maintenance." (PMID 32006464, 2020). "Blocking MYC activity causes tumor regression by promoting cell cycle arrest and differentiation." (PMID 31399583, 2019). "Indeed, overexpression of MYC has been shown to render tumor cells susceptible to chemotherapeutics, such as etoposide, doxorubicin, and camptothecin." (PMID 31886273, 2019). "Together, these findings suggest that during tumor maintenance MYC maintains large domains of active chromatin, and that tumor regression upon MYC inactivation is tightly linked to changes in expression of chromatin modifiers resulting in genome-wide changes to chromatin structure." (PMID 31266538, 2019). "We hypothesized that the genetic heterogeneity of c-MYC GCN in each tumor cell might be the cause of discrepancy between the SISH and ddPCR results." (PMID 30733532, 2019). "c-MYC is a DNA-binding transcription factor that regulates numerous genes involved in critical biological processes, being upregulated in several human cancer types, and associated with tumour aggressiveness and poor clinical outcome." (PMID 31461477, 2019). "Similarly, PIM inhibition has previously been suggested as a therapeutic option in MYC/MYCN‐associated tumor types." (PMID 31310053, 2019). "Moreover, the chromosome conformation capture assay demonstrated that the risk region interacted with MYC in the long-range physical way, leading to tumor development." (PMID 31309249, 2019). "Indeed, upregulation of MYC-mediated de novo purine synthesis maintained self-renewal, proliferation and tumor forming capacity in brain TICs, and was associated with poor prognosis in glioblastoma patients." (PMID 30967773, 2019). "However, these inhibitors affect hundreds of targets resulting in poor selectivity and quick tumor-adaptative response in acute myeloid leukemia models and other cancer models, causing MYC levels to remain unchanged." (PMID 30076412, 2019). "Tumours with high MYC and low ATM expressions were significantly associated with higher tumour grade, tumour type, pleomorphism, high mitotic index, ER−, PR−, triple negative, basal phenotypes and high-risk Nottingham Prognostic Index (NPI) (all adjusted p values ≤ 0.001)." (PMID 30746633, 2019). "Thus, SIRT2 and MYC are implicated in tumour metabolism regulation of MYC-induced malignancies working as a positive feedback loop." (PMID 30356832, 2018). "MYC and miR-17∼92 have been implicated in modulation of anti-tumor immune response." (PMID 29464015, 2018).